PCOLCE2 (procollagen C-endopeptidase enhancer 2)
Description:
Binds to the C-terminal propeptide of types I and II procollagens and may enhance the cleavage of that propeptide by BMP1.
Synonyms: PCPE2
Tractability: Antibody: UniProt places it where antibodies can reach, with high confidence; UniProt predicts a signal peptide or a membrane-spanning region; its Gene Ontology location is reachable by antibodies, with medium confidence. PROTAC: its protein half-life has been measured.
Gene: Protein-coding gene on chromosome 3 (142,815,922 to 142,889,206, reverse strand). Ensembl gene ENSG00000163710.
Subcellular location: Secreted
Subcellular location (Human Protein Atlas): Cytosol; Nucleoplasm; Predicted to be secreted
Pathways (Reactome):
Extracellular matrix organization: Collagen biosynthesis and modifying enzymes
Gene Ontology:
Molecular function: collagen binding; heparin binding; peptidase activator activity; protein binding
Cellular component: non-collagenous component of interstitial matrix; extracellular region
Genetic constraint (gnomAD): Loss-of-function variants: 14 observed, 20.58 expected, observed/expected ratio (o/e) 0.68, 90% interval 0.45 to 1.06. The upper end of that interval is the gene's LOEUF score, 1.06, which puts it in group 4 of 6, group 1 being the genes least tolerant of losing a copy. Missense variants: 298 observed, 308.92 expected, observed/expected ratio (o/e) 0.96, 90% interval 0.88 to 1.06. Synonymous variants: 107 observed, 114.87 expected, observed/expected ratio (o/e) 0.93, 90% interval 0.8 to 1.09.
Homologues: Orthologues: macaque PCOLCE2 (98% identical), chimpanzee PCOLCE2 (97% identical), rabbit PCOLCE2 (92% identical), pig PCOLCE2 (92% identical), rat PCOLCE2 (88% identical), mouse Pcolce2 (87% identical), tropical clawed frog pcolce2 (79% identical), dog PCOLCE2 (75% identical), guinea pig PCOLCE2 (73% identical), zebrafish pcolce2b (71% identical), zebrafish pcolce2a (62% identical). Paralogues in human: PCOLCE (44% identical), CUBN (30% identical), CDCP2 (30% identical), CNTNAP4 (18% identical), CNTNAP5 (17% identical), F5 (17% identical), CNTNAP2 (16% identical), CNTNAP3 (16% identical), CNTNAP3B (16% identical), F8 (16% identical), CP (15% identical), NRP1 (14% identical), and 23 more.